FAM135A (family with sequence similarity 135 member A)
Synonyms: KIAA1411; FLJ20176
Tractability: PROTAC: ubiquitination databases record sites on it.
Gene: Protein-coding gene on chromosome 6 (70,412,941 to 70,561,608, forward strand). Ensembl gene ENSG00000082269.
Subcellular location (Human Protein Atlas): Nucleoplasm; Cytosol
Pathways (Reactome):
Signal Transduction: RND1 GTPase cycle
Gene Ontology:
Biological process: lipid metabolic process
Genetic constraint (gnomAD): Loss-of-function variants: 66 observed, 117.15 expected, observed/expected ratio (o/e) 0.56, 90% interval 0.46 to 0.69. The upper end of that interval is the gene's LOEUF score, 0.69, which puts it in group 2 of 6, group 1 being the genes least tolerant of losing a copy. Missense variants: 1,483 observed, 1,668.7 expected, observed/expected ratio (o/e) 0.89, 90% interval 0.85 to 0.93. Synonymous variants: 525 observed, 589.46 expected, observed/expected ratio (o/e) 0.89, 90% interval 0.83 to 0.96.
Homologues: Orthologues: macaque FAM135A (98% identical), chimpanzee FAM135A (98% identical), rabbit FAM135A (91% identical), dog FAM135A (91% identical), pig FAM135A (90% identical), guinea pig FAM135A (85% identical), mouse Fam135a (84% identical), rat Fam135a (82% identical), tropical clawed frog fam135a (63% identical), zebrafish fam135a (50% identical), Drosophila melanogaster CG32333 (30% identical), Caenorhabditis elegans C09D4.4 (15% identical). Paralogues in human: FAM135B (36% identical).
Diseases named in the same sentence as FAM135A in open-access papers:
FAM135A is named in the same sentence as 15 diseases in open-access papers, as found by Europe PMC text mining. Sharing a sentence is not in itself a finding about the gene and the disease. The quoted sentences say what the papers report.
breast carcinoma (1 paper, 2023). "FAM135A is linked to several tumor-related pathways and is strongly correlated with breast cancer cell invasion and migration, according to extensive bioinformatics and experimental studies." (PMID 36943627, 2023). "Furthermore, Kaplan–Meier survival analysis indicates that FAM135A expression is favorably associated with prognosis and negatively associated with stage in patients with breast cancer." (PMID 36943627, 2023). "FAM135A knockdown enhances breast cancer cell proliferation and clone creation, as well as two-dimensional and three-dimensional migratory capacities." (PMID 36943627, 2023). "FAM135A is found to increase the proliferation and migration of breast cancer cells when it is down-regulated." (PMID 36943627, 2023). "The goal of this research is to look at the interaction between MIR17HG and FAM135A expression in breast cancer cells, as well as the link between MIR17HG expression and breast cancer cell proliferation and migration, as well as possible mechanism." (PMID 36943627, 2023). "Consistent with the previous assumption, our data demonstrated MIR17HG/miR-454-3p/FAM135A axis functions aslncRNA-miRNA-mRNA network through ceRNA mechanism in breast cancer." (PMID 36943627, 2023). "The knockdown effectiveness of shRNA designed to knock down FAM135A in breast cancer cells is evaluated using qPCR, which reveals that FAM135A shRNA is successful." (PMID 36943627, 2023). "This study will help clarify the mechanism of LncRNA MIR17HG in the incidence and development of breast cancer, as well as future research on the molecular mechanism of FAM135A in breast cancer invasion and metastasis." (PMID 36943627, 2023). "Our findings reveal the function of MIR17HG/miR-454-3p/FAM135A axis in breast cancer and provide potential novel therapeutic targets for metastatic breast cancer intervention." (PMID 36943627, 2023). "In this study, we discovered that MIR17HG/miR-454-3p/FAM135A axis functions in preventing development and metastasis in breast cancer." (PMID 36943627, 2023). "Following transfection with the miR-454-3p inhibitor to reduce miR-454-3p expression, the mRNA expression level of FAM135A in breast cancer cells is enhanced." (PMID 36943627, 2023). "Using Transwell assays, we then look at how FAM135A affects breast cancer cell migration." (PMID 36943627, 2023). "Patients with high FAM135A expression in their breast cancer had a better prognosis." (PMID 36943627, 2023). "These novel findings indicate that MIR17HG/miR-454-3p/FAM135A axis may be a potential target for breast cancer therapy to improve the survival time and quality of life of patients." (PMID 36943627, 2023). "FAM135A expression was lower in breast cancer tissues than in normal tissues adjacent." (PMID 36943627, 2023). "This gene was also enriched in the pathway related to “Cancer-Related”, and we speculate that FAM135A may play a key role in the pathogenesis of breast cancer through JAK-STAT signaling pathway." (PMID 36943627, 2023). "MIR17HG knockdown reduces FAM135A mRNA expression in breast cancer cells, but MIR17HG overexpression enhances FAM135A mRNA expression." (PMID 36943627, 2023).
oral cancer (1 paper, 2024). "Moreover, SCC15-specific upregulation was observed with KCNA4 and SRGAP2 and downregulation among SCC15 cells of FAM135A, which was observed among all other oral cancer cell lines." (PMID 38396844, 2024). "However, three miR-145 downstream targets were identified in the least chemotherapy-resistant cells, exhibiting the differential upregulation of KCNA4 and SRGAP2, as well as the downregulation of FAM135A, with this expression pattern not detected in any of the other oral cancer cell lines." (PMID 38396844, 2024).
infection (1 paper, 2019). The state of being infected such as from the introduction of a foreign agent such as serum, vaccine, antigenic substance or organism. "The results showed that DYRK1A, FAM135A, PLAG1, ZNF148, and PHC3 were obviously inhibited at infection times of 3 h, 6 h, and 9 h pi." (PMID 31784561, 2019).
FAM135A also shares sentences with these, for which no sentence is quoted: cancer (3 papers); pancreatic cancer (2); tumor (2); colorectal cancer (1); glioma (1); Huntington disease (1); neurodegenerative disease (1); Obesity (1); Parkinson disease (1); prostate carcinoma (1); renal cell carcinoma (1); type 2 diabetes (1).